AIM2 (absent in melanoma 2)
Diseases named in the same sentence as AIM2 in open-access papers (continued):
Sharing a sentence is not in itself a finding about the gene and the disease.
inflammatory bowel disease (7 papers, 2020 to 2025). A spectrum of small and large bowel inflammatory diseases of unknown etiology. "As an example, it would be interesting to see whether genetic variations (methylation status, single nucleotide polymorphisms, etc.)affecting AIM2 gene expression or function are associated with the susceptibility to Treg-associated diseases in humans, such as inflammatory bowel disease." (PMID 35216346, 2022). "IRF1 upregulates multiple PANoptosome components, including ZBP1, RIPK1, and AIM2, driving PANoptosis in models of inflammatory bowel disease (IBD) and alcoholic liver disease." (PMID 41583472, 2025). "In conclusion, we systematically summarized the landscape of pyroptosis in inflammatory bowel disease and identified AIM2, CASP1, CASP5, GSDMD, and NLRP3 as hub genes." (PMID 37740137, 2023). "In active inflammatory bowel disease, a significant two‐fold higher expression of AIM2 and IFI16 is observed in the intestinal mucosa compared with controls, indicating priming/upregulation of these proteins in certain conditions involving barrier function integrity." (PMID 31850638, 2020). "The activation of AIM2 is closely associated with the onset and progression of various diseases, particularly in inflammatory bowel disease (IBD), where AIM2 expression is significantly upregulated, suggesting its potential role in disease progression." (PMID 40386782, 2025).
injury (7 papers, 2020 to 2024). Damage inflicted on the body as the direct or indirect result of an external force, with or without disruption of structural continuity. "It has been shown that cerebrospinal fluid induces the activation of neurons by AIM2 inflammasomes in patients with traumatic brain injury, suggesting that AIM2 may play a potential pathogenic role in neuronal disease." (PMID 36034843, 2022). "In radiation-induced acute lung injury, double-stranded DNA breaks induced by ionizing radiation, can activate pyroptosis through AIM2 inflammasome." (PMID 36177039, 2022). "Hence, it is believably accepted that AIM2 may be a detrimental factor in acute brain injury." (PMID 38714826, 2024). "AIM2 could damage neurons during ischemic and hemorrhagic injury via increasing neuroinflammation and oxidative stress after experimental SAH, hypoxic-ischemic brain injury, middle cerebral artery occlusion and traumatic brain injury." (PMID 38714826, 2024).
periodontal disease (7 papers, 2020 to 2024). "Genetic analysis of AIM2 G/T (rs2793845) revealed a high frequency of the (T) allele and (GT and TT) genotypes that were detected in the periodontal disease and coronary heart disease groups in males." (PMID 41194911, 2024). "The Pearson’s correlation coefficient results of this study indicate that AIM2 genetic variation is meaningfully associated with indicators of periodontal disease severity in periodontal disease patient groups." (PMID 41194911, 2024). "We identified polymorphisms in inflammasome genes interferon gamma inducible protein 16 (IFI16) and absent in melanoma 2 (AIM2) that were associated with increased severity of periodontal disease." (PMID 32533779, 2020). "Additionally, indicators of periodontal disease severity and the AIM2 gene showed a significant association." (PMID 41194911, 2024). "Thus, further and longitudinal studies are essential to investigate and explore the function of AIM2 gene polymorphisms as the prognostic and therapeutic implications in the progression of periodontal disease and CHD." (PMID 41194911, 2024). "In addition, the association of T alleles of the AIM2 SNP with the probability of periodontal diseases and/or coronary heart disease has been assessed, which suggests the validity of this SNP as a putative genetic risk factor for both diseases in the Iraqi population." (PMID 41194911, 2024). "Thus, understanding how variants of IFI16 and AIM2 contribute to periodontal disease pathogenesis may lead to treatment options that address individual biological variations and precision therapies for oral health." (PMID 32533779, 2020). "The AIM2 SNP was also found to be significantly correlated with indicators of periodontal disease severity." (PMID 41194911, 2024). "Pearson correlation test coefficients (r) calculated between AIM2 G/T (rs2793845) and indicators of periodontal disease for the study groups." (PMID 41194911, 2024). "A genome-wide association study (GWAS) found that AIM2 and IFI16 single-nucleotide polymorphisms (SNPs) are associated with increased clinical parameters of periodontal disease, increased levels of gingival crevicular fluid IL-1β, and higher bacterial loads." (PMID 32903550, 2020). "Current evidences regarding AIM2 inflammasome in oral diseases mainly focused on periodontal diseases, dental pulpitis, and OSCC." (PMID 32903550, 2020). "There are limited data exploring the role of IFI16 and AIM2 in periodontal disease pathogenesis." (PMID 31850638, 2020). "Increased expression of NLRP3 and AIM2 in the gingival tissues of patients with periodontal disease is positively correlated with the levels of IL-1β and IL-18, suggesting that various inflammasomes may participate in the microbial-induced inflammation in periodontal diseases." (PMID 32385413, 2020). "This sheds insight into the current investigation, which aims to determine the relationship between AIM2 gene polymorphisms and periodontal disease propensity in both people with and without CHD, and to detect whether males or females are more susceptible to these diseases." (PMID 41194911, 2024). "Considering the correlation between AIM2 genetic substitution and disease severity, our findings not only shed light on disease progression but also suggest a novel approach for treating periodontal disease and coronary heart disease." (PMID 41194911, 2024). "Studies have revealed that nucleotide‐binding and oligomerization domain‐like receptor (NLR) pyrin domain‐containing 3 (NLRP3) and absent in melanoma 2 (AIM2) inflammasome are involved in periodontal disease pathogenesis." (PMID 37506160, 2023).
rheumatoid arthritis (7 papers, 2020 to 2026). A chronic, systemic autoimmune disorder characterized by inflammation in the synovial membranes and articular surfaces. "Among them, melanoma deficiency factor 2 (AIM2) recognizes damaged DNA and double-stranded DNA and binds to them to further assemble inflammasome, initiating the innate immune response and participating in the pathophysiological process of rheumatoid arthritis." (PMID 39450183, 2024). "In this article, we review the research progress on the source of cytoplasmic DNA, the mechanism of assembly and activation of AIM2 inflammasome, and the related roles of other cytoplasmic DNA sensors in rheumatoid arthritis." (PMID 39450183, 2024). "In rheumatoid arthritis (RA), patients exhibited reduced levels of AIM2 in their sera compared to healthy individuals, whereas levels of ASC, Caspase-1, and IL-1β are elevated." (PMID 39600708, 2024). "Our understanding of the AIM2 inflammasome’s role in pathogenesis has been furthered by observations of its upregulated expression, alongside that of ASC and Caspase-1, in PBMCs and neutrophils of rheumatoid arthritis patients." (PMID 39100670, 2024).
Sjögren’s syndrome (7 papers, 2013 to 2026). "In Sjögren syndrome (SS), a chronic inflammatory disorder, aberrant activation of the NLRP3 and AIM2 inflammasome pathway was confirmed." (PMID 41440367, 2025). "Thus, NLRP3, AIM2 and IFI16 are components of the innate immune system that are activated in Sjögren syndrome." (PMID 41440367, 2025).
acute kidney injury (6 papers, 2022 to 2025). Sudden and sustained deterioration of the kidney function characterized by decreased glomerular filtration rate, increased serum creatinine or oliguria. "In herpes simplex virus 1 (HSV-1) infection or cisplatin-induced acute kidney injury, AIM2 cooperates with ZBP1 to activate the caspase-8/GSDME axis." (PMID 41583472, 2025). "Our data suggest the AIM2 and Dectin-1 inflammasome pathways, along with complement cascade elements C2 and C8, and lipidic disorders associated with apolipoprotein C-II (APOC2), can be associated with the development of renal failure in Bothrops snakebites." (PMID 38536893, 2024). "In conclusion, this study shows that the inhibition of Calpain 1 and 2 activity by calpeptin plays a nephroprotective role in ischemia/reperfusion-induced acute kidney injury by suppressing AIM2 and NLRP3 inflammasome activation and by upregulating Klotho protein." (PMID 35155498, 2022). "Subsequent experiments within this study demonstrated that AIM2-induced pyroptosis effectively inhibited the pro-inflammatory STING/CXCL10/CXCR3 signaling pathway both in vivo and in vitro, consequently attenuating inflammation associated with acute kidney injury." (PMID 39600708, 2024). "The calpain-mediated AIM2 inflammasome signaling pathway and distinct interaction between calpain and Klotho may provide a potential novel preventative and therapeutic target for acute kidney injury." (PMID 35155498, 2022). "Pretreatment of roxadustat (10 mg/kg/day in vivo and 10 μM in vitro) protects against ischemia-induced acute kidney injury (AKI) via improving CD73 and decreasing AIM2 inflammasome activation." (PMID 40040789, 2025). "However, the role of AIM2 inflammasome activation in acute kidney injury remains unclear." (PMID 35155498, 2022). "Similarly, in the context of rhabdomyolysis induced acute kidney injury (RIAKI), it was observed that macrophages deficient in AIM2 did not regulate dsDNA-induced pyroptosis but instead activated alternative DNA sensing pathways, such as STING, resulting in heightened inflammation and fibrosis." (PMID 39600708, 2024).
aortic aneurysm (6 papers, 2020 to 2025). A ruptured aneurysm located in the wall of the proximal portion of the descending aorta proceeding from the arch of the aorta. "We recently demonstrated that Aim2 deficiency affects the phenotype of murine aortic VSMC, thereby reducing AngII-induced formation of aortic aneurysm in six month old mice." (PMID 34572082, 2021). "Additionally, components of AIM2 inflammasome are increased in infiltrating lymphoid cells in the outer tunica media and adventitia of aortic samples from AAA patients, suggesting the involvement of AIM2 signaling in immune cells during aortic aneurysm." (PMID 39158380, 2025).
benign prostate hyperplasia (6 papers, 2015 to 2025). "The AIM2 mRNA levels were significantly higher in benign prostate hyperplasia (BPH) than the normal prostate." (PMID 33923931, 2021). "AIM2 activation in response to the cytosolic dsDNA also plays a significant role in benign prostate hyperplasia (BPH) independent of androgen receptor status." (PMID 33643304, 2020). "Further, DHT-mediated activation of the AR in human PrECs and in a benign prostate hyperplasia (BPH) cell line (BPH-1) up-regulated the expression of POP3 protein and inhibited cytosolic DNA-induced activation of the AIM2 inflammasome." (PMID 33923931, 2021). "Similarly, treatment of human benign prostate hyperplasia cell line BPH-1 with 10 nM DHT also increased the levels of IFI16 and POP3 proteins, but not AIM2 protein (data not shown)." (PMID 33923931, 2021).
depression (6 papers, 2022 to 2025). "The AIM2 inflammasome has also emerged as a significant player in neuroinflammatory processes associated with depression." (PMID 40305200, 2025). "Recent findings suggest that AIM2 is activated by various stressors, including LPS, leading to a chronic neuroinflammatory state that contributes to the pathogenesis of depression." (PMID 40305200, 2025). "First, current studies on pyroptosis and neurological diseases are limited to NLRP3 and AIM2 inflammasomes, and the link between other types of pyroptosis-related inflammasomes, such as NLRC4, NLRP6, and depression, needs to be further investigated and elucidated." (PMID 35722622, 2022).
glomerulonephritis (6 papers, 2013 to 2023). A renal disorder characterized by damage in the glomeruli. "We hypothesized that AIM2 expression is positively correlated with HBV-mediated inflammation in patients with HBV-associated glomerulonephritis (HBV-GN), potentiating inflammation and leading to renal damage." (PMID 24701032, 2014). "AIM2 expression was detected in 81% of renal biopsies from patients with HBV-associated glomerulonephritis, but only in 4% of biopsies from HBV-unrelated glomerulonephritis." (PMID 32906750, 2020). "Similar AIM2 effects were observed in patients with HBV-induced glomerulonephritis, suggesting an important central role of AIM2 in contributing to inflammatory damage and severe disease progression." (PMID 28740569, 2017). "Upregulated AIM2 significantly correlates with increased inflammation in chronic HBV infection, and this was found to induce renal damage in the presence of glomerulonephritis." (PMID 28740569, 2017).
Hypertension (6 papers, 2022 to 2025). The presence of chronic increased pressure in the systemic arterial system. "While AIM2 senses nuclear or cytosolic DNA and has been implicated in mouse models of hypertension and aneurysm, its relevance in human cardiovascular disease is still unclear." (PMID 41488670, 2025). "Hypertension has been increasingly linked to multiple inflammasomes, including NLRP3, AIM2, and NLRC4, contributing to vascular dysfunction and blood pressure regulation." (PMID 40433411, 2025). "Interestingly, chrysanthemum indicum extract, a traditional herbal medicine using for hypertension, inhibits NLRP3 and AIM2 inflammasome activation via regulating ASC phosphorylation in mice." (PMID 40433411, 2025). "The subgroup analysis of serum AIM2 level and DCI showed that there were no significantly different interactions between serum AIM2 levels and other variables, such as age, gender, hypertension, smoking, and alcohol drinking." (PMID 38714826, 2024). "We further analyzed interactions of serum AIM2 levels on age, sex, hypertension, smoking and drinking, and found that no significantly statistical interactions existed (all P > 0.05)." (PMID 38714826, 2024). "Although a direct link between AIM2 inflammasome and hypertension has not been established, it has been shown that AIM2 is related to endothelial dysfunction, a significant factor in the development and progression of hypertension." (PMID 40433411, 2025). "Thus, no changes in intrarenal AIM2 levels in Ang II-infused rats are expected and the results highlight specific regulation of renal NLRP3 in hypertension." (PMID 35887028, 2022).
inflammatory skin disease (6 papers, 2015 to 2025). Inflammatory skin disorders covers a broad category that includes many conditions ranging in severity, from mild itching to grave medical health complications These disorders are common in people of all ages and races. "Among these, extensive research has focused on the roles of inflammasomes formed by NLR family members (e.g., NLRP1 and NLRP3) and the AIM2-like receptor family member AIM2 in inflammatory skin diseases." (PMID 41383588, 2025). "Aim2 (3.67-fold increase) is known to form inflammasome complexes in response to cytoplasmic dsDNA in inflammatory skin disease." (PMID 34445339, 2021).
influenza (6 papers, 2018 to 2025). An acute viral infection of the respiratory tract, occurring in isolated cases, in epidemics, or in pandemics; it is caused by serologically different strains of viruses (influenzaviruses) designated A, B, and C, has a 3-day incubation period, and usually lasts for 3 to 10 days. "As AIM2 expression can be upregulated with IFN-gamma signaling, and IFN-g + TFH cells peak at 10 days post influenza infection, we asked if AIM2 was expressed in GC B cells following influenza infection." (PMID 40825032, 2025). "As we observe the majority of GC B cells expressing AIM2, we sought to investigate if AIM2 has a significant functional role on the GC, following influenza infection." (PMID 40825032, 2025). "Another group showed that DNA in the microenvironment of the lung during influenza infection can trigger AIM2, adding to the research suggesting pyroptosis and inflammasome activation is a circular process." (PMID 36298668, 2022). "Understanding the nuances of AIM2’s involvement could unveil novel therapeutic avenues for mitigating severe influenza outcomes." (PMID 39459869, 2024). "Besides NLRP3, influenza has also been shown to activate RIG-I (which promotes replication) and AIM2." (PMID 36298668, 2022). "Multiple inflammasomes can be involved in IL-1β activation, including NLRP3, NLRP1, NLRC4, AIM2, IFI16 and RIG-I, however because GC B cells are not directly infected by influenza infection, we examined NLRP3 and AIM2 as they are activated by stimuli likely to be present in GC B cells." (PMID 40825032, 2025).
Insulin resistance (6 papers, 2021 to 2025). Increased resistance towards insulin, that is, diminished effectiveness of insulin in reducing blood glucose levels. "In T2D, AIM2 exacerbates insulin resistance through its inflammasome‐dependent cytokines, while in T1D, it provides a protective effect against disease progression by maintaining gut integrity." (PMID 39158380, 2025). "Our study showed that AIM2 deletion induces spontaneous obesity and insulin resistance in mice." (PMID 40433411, 2025). "Furthermore, AIM2 knockout led to insulin resistance and glucose intolerant." (PMID 38469147, 2024). "Taken together, these findings suggest that inflammasomes, including NLRP3, AIM2, NLRP1, NLRP6 and NLRC4 inflammasomes are involved in the regulation of insulin resistance, pancreatic β-cell health and diabetes." (PMID 40433411, 2025).
ischemia (6 papers, 2020 to 2024). A hypoperfusion of the BLOOD through an organ or tissue caused by a PATHOLOGIC CONSTRICTION or obstruction of its BLOOD VESSELS, or an absence of BLOOD CIRCULATION. "AIM2 deletion in brain endothelial cells reversed ischemia‐induced BBB injury by suppressing ICAM‐1 expression and neutrophil adhesion in a STAT3 signaling‐ dependent manner." (PMID 34156153, 2021). "To further investigate and validate our in vivo findings, we examined microglial cells and astrocytes in an in vitro ischemia model with respect to AIM2 and NLRC4 expression." (PMID 32645874, 2020). "Overall, our study signifies a critical turning point in understanding the regulation of AIM2-pyroptosis and mitophagy under ischemia–reperfusion conditions, supporting the exploration of Sirt6-enriched adipose stem cell-derived exosomes as a practical clinical treatment." (PMID 38172884, 2024). "Moreover, functional inhibition of NLRP3 is compensated by an upregulation of NLRC4 and AIM2 after ischemia." (PMID 34628598, 2022). "Therefore, we measured the expression of ICAM‐1 in the context of AIM2 deletion and found that both MCAO and OGD/R increased ICAM‐1 expression, whereas inhibiting AIM2 reversed these effects, suggesting that AIM2 deletion prevents ischemia‐induced BBB injury by downregulating ICAM‐1 expression." (PMID 34156153, 2021). "We demonstrate that AIM2 and NLRC4 are upregulated after ischemia and E2 + P seem to downregulate AIM2, while NLRC4 seems to be lowered only by E2." (PMID 32645874, 2020). "Besides NLRP3, AIM2 and NLRC4 seem to play a crucial role after ischemia and are regulated by E2 and P." (PMID 32645874, 2020).